FGF21 (fibroblast growth factor 21)
Diseases named in the same sentence as FGF21 in open-access papers (continued):
Sharing a sentence is not in itself a finding about the gene and the disease.
type 1 diabetes (26 papers, 2013 to 2026). "NRF-2 induced hepatic FGF-21 expression and secretion in obese mice and even protected the liver against oxidative stress, while FGF-21 deficiency enhanced type 1 diabetes-induced oxidative stress in the heart." (PMID 33317180, 2020). "In this study, for the first time we established that FGF21 deletion is susceptible to develop DCM in STZ-induced type 1 diabetic mice, which is predominantly attributed to the exacerbated cardiac lipid accumulation via Nrf2 up-regulation of CD36-mediated cardiac fatty acid accumulation." (PMID 25823710, 2015). "Thus, FF may prevent cardiac pathology and functional abnormalities caused by type 1 diabetes by increasing FGF21 levels, which may upregulate SIRT1-mediated autophagy." (PMID 36843938, 2023). "The fenofibrate-induced cardioprotective function of FGF21 in type-1 diabetes is correlated to Sirt1, another upregulated target of fenofibrate, which rescues disrupted autophagy." (PMID 34095143, 2021). "FGF21 protects against renal dysfunction and testicular apoptotic cell death in murine models of type 1 diabetes, and prevents diabetic nephropathy." (PMID 32872333, 2020). "It has been observed that FGF21 has a beneficial effect on the kidneys of mice with type 1 diabetes, because it prevents oxidative stress, inflammation, apoptosis, and fibrosis." (PMID 30927227, 2019). "Our previous studies showed that both exogenous and endogenous FGF21 inhibited cardiac apoptosis at the early stage of type 1 diabetes." (PMID 29445083, 2018). "FF has been shown to prevent type 1 diabetes-induced pathological and functional abnormalities of the heart by increasing FGF21, which may up-regulate Sirt1-mediated autophagy." (PMID 38312833, 2024). "Some studies have shown associations between FGF21 and nephropathy and retinopathy in type diabetes whereas another study of elderly patients with type 1 diabetes showed no such association." (PMID 38932813, 2024). "In a recent study where optical coherence tomography angiography (OCTA) was used, higher levels of FGF21 were found in children and adolescents with type 1 diabetes (n = 100) compared to the same number of age, gender, and Tanner-matched healthy controls (n = 100)." (PMID 38932813, 2024). "Stepwise multiple linear regression analysis of FGF21 in type 1 diabetes patients." (PMID 35192641, 2022). "Moreover, FGF21 was shown to inhibit the induction of apoptosis of cardiomyocytes occurring during type-1 diabetes." (PMID 34095143, 2021). "However, FGF21 level in the case of type 1 diabetes and latent autoimmune diabetes of adults (LADA) was significantly lower than in a healthy control group." (PMID 30927227, 2019). "Thus, FGF21 prevents type 1 diabetes-induced pathological and functional cardiac abnormalities by up-regulating sirtuin 1-mediated autophagy." (PMID 27803896, 2016). "Cardiac FGF21 expression is increased in a mouse model of type 1 diabetes." (PMID 27803896, 2016). "In the retina, long-acting FGF21 (PF-05231023) was reported to decrease pathological retinal vessel proliferation and promote physiological retinal vascularization in a murine oxygen-induced retinopathy model and protect against retinal neural dysfunction in a type 1 diabetic mouse model." (PMID 32872333, 2020). "The first aim of this study was to investigate plasma levels of FGF21, Cystatin C, lipocalin 2 and MMP-9 in children and adolescents with different duration of type 1 diabetes." (PMID 38932813, 2024). "In a sub-group of patients with type 1 diabetes blood was drawn at time of and after diagnosis, with a mean time between samplings 1.3 ± 0.5 years (n = 42), the trajectory of circulating Cystatin C, MMP-9, lipocalin-2 and FGF21 was analysed." (PMID 38932813, 2024).
type 1 diabetes (continued). "This study aimed to investigate plasma levels of FGF21, Cystatin C, lipocalin-2, and MMP-9 in children and adolescents with different duration of type 1 diabetes and possible correlation to HbA1c to identify potential biomarkers of future complication development." (PMID 38932813, 2024). "FGF21 was also higher among patients with type 1 diabetes and OCTA changes compared to those without." (PMID 38932813, 2024).
Nephropathy (24 papers, 2011 to 2025). A nonspecific term referring to disease or damage of the kidneys. "Fibroblast growth factor 21 (FGF21) is deemed to play an important role in kidney outcomes, while the association between FGF21 and various kidney diseases remains largely unclear and inconsistent." (PMID 37009852, 2023). "Second, the number of eligible studies on the association between high FGF21 levels and other renal disease outcomes was very limited, leading to the instability of the conclusion of this part." (PMID 37009852, 2023). "For the research significance, our study has pointed out the necessity and urgency for researching the potential pathogenic effects of FGF21 in renal diseases." (PMID 37009852, 2023). "Although the outcome of the subgroup based on study design demonstrated that both cross-section and cohort study showed the inverse relationship between FGF21 and risk of renal disease, a more well-designed cohort is urgent to improve or deny our findings." (PMID 37009852, 2023). "And the study design of the included studies contained cross-sectional and cohort design, it is known that a cross-sectional study cannot establish a causal relationship between FGF21 and kidney disease." (PMID 37009852, 2023). "Description of eligible studies reporting the association between FGF21 and other renal diseases." (PMID 37009852, 2023). "The association between FGF21 and kidney disease has also been a concern in recent years." (PMID 34918690, 2021). "GDF15 was associated with nephropathy (p = 0.011) and PVD (p = 0.035), while FGF21 showed a strong association with nephropathy (p < 0.001)." (PMID 40629349, 2025). "FGF21 exerts renoprotective effects against cisplatin‐induced acute kidney injury and salt‐sensitive hypertension‐induced nephropathy." (PMID 39887648, 2025). "In the context of salt-sensitive hypertension, which is frequently associated with severe kidney damage and progression to end-stage kidney disease, FGF21 has been recognized as a suppressor of nephropathy in diabetic mice models." (PMID 38750219, 2024). "Elevated serum FGF21 levels were proposed as a useful biomarker for predicting the progression of renal disease, particularly in the early stages of DKD." (PMID 38312833, 2024). "Further clinical studies were needed to determine the critical role of FGF21 in renal outcomes to provide a more therapeutic target for renal diseases." (PMID 37009852, 2023). "Here, we aimed to investigate the therapeutic effect of FGF21 in salt-sensitive hypertension-induced nephropathy." (PMID 34773993, 2021). "We detected elevated expression levels of FGF21 progressing with age suggesting that metabolic stress response and disturbed mitochondrial function are a shared feature linking mitochondrial dysfunction to kidney damage in both OAs." (PMID 39681572, 2024). "Moreover, studies indicated that the deletion of FGF21 in mice exacerbated deoxycorticosterone acetate (DOCA)-salt-induced nephropathy." (PMID 38312833, 2024). "Moreover, FGF-21 has been shown to increase in numerous diseases, e.g., nephropathy, where levels correlate with plasma, blood urea nitrogen, and creatinine as well as proteinuria." (PMID 37371508, 2023). "The influence of FGF21 knockout in mice on DOCA-salt-induced nephropathy were determined." (PMID 34773993, 2021). "FGF21 resulted more elevated in presence of nephropathy or cardiac ischemia." (PMID 33131010, 2021). "Firstly, some data suggest that NAFLD may be the source of pro-inflammatory factors, including fetuin-A, plasminogen activator inhibitor-1 (PAI-1) and human fibroblast growth factor-21 (FGF-21), which may cause kidney damage." (PMID 33584144, 2021). "We found that deletion of FGF21 in mice aggravated DOCA-salt-induced nephropathy." (PMID 34773993, 2021). "Fibroblast growth factor 21 (FGF21) plays a role in kidney disease." (PMID 34918690, 2021). "Therefore, we conducted this meta-analysis to find out the role of FGF21 in various renal diseases." (PMID 37009852, 2023).
Nephropathy (continued). "Besides, DOCA-salt treatment led to a drastic up-regulation in both circulating levels and renal expression of FGF21, suggesting that FGF21 may be involved in the pathogenesis of salt-sensitive hypertensive-induced kidney damage." (PMID 34773993, 2021). "Therefore, we speculated that DOCA-salt-evoked increasing expression of FGF21 may represent a stress protection for the kidney to defend against DOCA-salt-induced kidney damage." (PMID 34773993, 2021).
Stroke (24 papers, 2016 to 2025). Sudden impairment of blood flow to a part of the brain due to occlusion or rupture of an artery to the brain. "FGF21 deficiency leads to neurological deterioration after stroke, which is partly attributed to excessive immune responses that are amplified from astrocytes to recruited leukocytes." (PMID 40021824, 2025). "Here, we show that the improved stroke recovery in the T2D-E group was associated with elevated post-stroke FGF-21 serum levels." (PMID 38424560, 2024). "Taken together, these results indicate that stroke decreases serum FGF-21 levels independently of the metabolic state of the animals, and that Empagliflozin prevents this stroke-induced reduction, in association with improved recovery." (PMID 38424560, 2024). "Increased FGF-21 levels have been associated with post-stroke recovery." (PMID 38424560, 2024). "Interestingly, FGF-21 has been positively associated with improved stroke recovery, both in pre-clinical and clinical studies." (PMID 38424560, 2024). "Given that glutamate overflow and excitotoxicity have been strongly implicated in stroke pathology, we used primary rat cortical neuronal cultures to assess the effects of TubA and FGF-21 on exogenous glutamate-induced excitotoxicity to explore any possible underlying protective mechanisms." (PMID 26790818, 2016). "FGF21 levels in the serum of stroke patients were substantially increased in the acute period after stroke onset compared with those in the control group." (PMID 40021824, 2025). "Here, we found elevated serum levels of FGF21 in stroke patients and transient middle cerebral artery occlusion (tMCAO) mice." (PMID 40021824, 2025). "Recent studies highlight its neuroprotective, anti-inflammatory, and pro-repair effects of FGF21 in ischemic brain injury, making it a promising therapeutic candidate for stroke recovery." (PMID 40581646, 2025). "In clinical practice, we found that endogenous FGF21 was robustly upregulated in the serum of stroke patients and animal models." (PMID 40021824, 2025). "Our observation of markedly elevated serum levels of FGF21 in stroke patients and transient middle cerebral artery occlusion (tMCAO) mice established a rationale for further investigation of the role of FGF21 in the pathological progression of brain ischemia." (PMID 40021824, 2025). "These benefits were observed even when FGF21 was administered a week after stroke induction, highlighting its high therapeutic potential." (PMID 40407975, 2025). "The grip strength test revealed that deficits in forelimb strength after stroke were exacerbated in FGF21−/− mice at 1, 7, 11, and 14 d postinjury." (PMID 40021824, 2025). "Female patients with middle and high FGF21 concentration had also significantly increased prevalence of stroke incidents." (PMID 39302236, 2024). "Similar effects were observed in diabetic mice with a post-stroke administration of recombinant FGF-21." (PMID 38424560, 2024). "At two weeks after stroke, FGF-21 levels were significantly decreased in both non-T2D and T2D-VH mice and remained significantly lower than pre-stroke levels in T2D-VH (p = 0.01) at five weeks post-stroke." (PMID 38424560, 2024). "FGF-21 is an important regulator of glucose and lipid metabolism, that has also been shown to have beneficial effects on stroke recovery." (PMID 38424560, 2024). "Higher concentrations of FGF21 on admission after stroke have also been reported in previous studies, in which the increase in FGF21 was maintained during the first 2 weeks after brain injury." (PMID 35207221, 2022). "FGF21 administration after cerebral infarction effectively reduced the production of inflammatory cytokines in stroke and peri-stroke regions in both groups." (PMID 35096806, 2021). "In the central nervous system (especially, the brain), recombinant human FGF21 improved ischemic outcomes in a murine model of stroke via alleviation of neuroinflammation." (PMID 33799938, 2021).
Stroke (continued). "Despite growing evidence on the neuroprotective and anti-inflammatory effects of FGF-21 against stroke, our study showed that R-7050 had little effects on the poststroke FGF-21 level." (PMID 34073455, 2021). "In this study, we investigated the mechanism of the effect of MHFD on stroke in offspring in adulthood and the mechanism by which FGF21 acts on stroke and restores neurological function." (PMID 35096806, 2021). "A recent study reported that FGF21 suppressed microglia/macrophage-mediated neuroinflammation in stroke." (PMID 33568994, 2020). "The secretion of FGF-21 likely also depends on transport within neurites, which is impaired by stroke." (PMID 26790818, 2016). "To assess the effects of pharmacological modulation of FGF21 on the astrocyte response after stroke, we subjected MCAO mice to intraperitoneal treatment with rhFGF21 at 12 h intervals starting after reperfusion and measured GFAP expression in the cortical areas adjacent to the infarcted region." (PMID 40021824, 2025). "Furthermore, in the Morris water maze test, compared with WT mice, FGF21−/− mice presented a longer swimming latency in the cued test, indicating a significant decline in spatial learning ability after stroke." (PMID 40021824, 2025). "Overall, FGF21 participates in regulating microglia-mediated neuroinflammation after stroke." (PMID 40021824, 2025). "The present study revealed that FGF21 levels were increased in the serum of stroke patients as well as in an experimental tMCAO mouse model and that glial cells such as microglia and astrocytes are another source of cerebral FGF21 after stroke in addition to neurons." (PMID 40021824, 2025). "Furthermore, an intervention with recombinant FGF-21, either acutely or in the chronic phase after stroke, significantly improved recovery in diabetic mice." (PMID 38424560, 2024). "Moreover, Jiang and colleagues recently demonstrated that a therapeutic administration of FGF-21 improves post-stroke recovery in diabetic mice." (PMID 38424560, 2024). "Interestingly the post-stroke treatment with Empagliflozin resulted in a significant increase of serum FGF-21 levels, both at two and at five weeks after stroke." (PMID 38424560, 2024). "FGF21 upregulates the PPARγ pathway to alleviate inflammation in microglia and macrophages and protect brain microvascular endothelial cells, playing a positive role in stroke." (PMID 38733164, 2024). "Like other FGFs, after a stroke, recombinant human FGF21 has anti‐inflammatory properties that attenuate inflammatory cell polarization and the infiltration of peripheral immune cells, showing its potential as an anti‐inflammatory agent in stroke." (PMID 36924298, 2023). "In the field of stroke, FGF21 is known for its protective effects." (PMID 35207221, 2022). "In this study, we found that higher concentrations of FGF21 on admission and RBM3 at 72 h were associated with good outcome and BMI, but inversely related to the maximum temperature during the first 24 h after stroke." (PMID 35207221, 2022). "Moreover, AMPK contributes to the anti-aging action of FGF21, contributing to the reduction of cerebrovascular aging-related diseases, such as stroke and neurodegenerative diseases." (PMID 35624759, 2022). "Fibroblast growth factor 21 (FGF21) has been reported to have a neuroprotective effect in stroke, but its mechanism of action remains unknown." (PMID 35096806, 2021). "Also, FGF21’s peripheral actions (e.g., hepatic lipid metabolism, cardiac protection) may synergize with CNS effects to improve post-stroke systemic recovery." (PMID 40581646, 2025). "Given the existing evidence, it is of particular interest to investigate how FGF21 could modulate age-related changes in cerebrovascular and brain function in aged organisms without underlying stroke or CNS injury." (PMID 40407975, 2025). "Therefore, although speculative, our results highlight FGF-21 as a potential mechanism for improved stroke recovery mediated by SGLT2i treatment." (PMID 38424560, 2024).
Stroke (continued). "To understand the relationship between FGF21 and RBM3 in a clinical scenario such as stroke, we evaluated the associations between the circulating concentrations of both proteins and the outcome of stroke patients, and how body weight and temperature influence this response." (PMID 35207221, 2022). "Additionally, FGF21 treatment effectively improves neurological function after stroke." (PMID 35096806, 2021). "In a mouse model of ischemic stroke, treatment with plasma from healthy mouse donors ameliorated stroke-induced BBB disruption, neuroinflammation, and neurological dysfunction through FGF21." (PMID 40407975, 2025). "Systemic administration of FGF21 alone restored BBB integrity, reduced neuroinflammation, protected white matter, and reduced infarct volume in the mouse model of stroke." (PMID 40407975, 2025). "Key proteins involved in mitochondrial stress, such as ATF5, ATF4, HSF1, FGF21, and GDF15, hold promise as potential targets for modulating neuroinflammation during stroke." (PMID 38321473, 2024). "In addition, although we showed a positive association between Empagliflozin-induced improvement in stroke recovery and increased FGF-21 levels, we did not address whether this is indeed a causative mechanism of improved functional recovery." (PMID 38424560, 2024). "Higher concentrations of FGF21 were found on admission, while the peak for RBM3 expression was observed 72 h after stroke onset." (PMID 35207221, 2022). "We have previously proposed a disease-modifying approach using recombinant fibroblast growth factor 21 (rFGF21) to treat ischemic stroke mice with T2DM and observed the beneficial effects of rFGF21 on long-term neurological outcomes in T2DM stroke mice." (PMID 32012810, 2020). "Nevertheless, detailed molecular mechanisms for FGF21-induced PPARγ activation and downstream signaling pathways of PPARγ activation in modulating BBB integrity after T2DM stroke need to be elucidated in future investigations." (PMID 32012810, 2020). "After FGF21 administration, WB and qPCR analyses showed that astrocytes and the PI3K/Akt pathway were upregulated, while NF-κB and inflammatory cytokines expression were inhibited in stroke and peri-stroke regions." (PMID 35096806, 2021). "However, the interaction between RBM3 and FGF21 has not yet been tested for clinical stroke conditions." (PMID 35207221, 2022). "The therapeutic potential of FGF21 in stroke has been indicated by studies in animal models; however, the main limitation for a future translational application is the side effects of other related factors, such as FGF2 and FGF23, in clinical trials with stroke patients." (PMID 35207221, 2022).